HDAC3 (histone deacetylase 3)
Diseases named in the same sentence as HDAC3 in open-access papers (continued):
Sharing a sentence is not in itself a finding about the gene and the disease.
atherosclerosis (continued). "Deletion of Hdac3 in macrophages shifted their phenotype to an atherosclerosis beneficial phenotype leading to enhanced collagen deposition and a stable plaque phenotype." (PMID 25007801, 2014). "HDAC3 also increases atherosclerotic plaque instability and inhibits cholesterol efflux from foam cells, which may play a role in the development of atherosclerosis." (PMID 40497340, 2025). "Additionally, HDAC3 protects against atherosclerosis by inhibiting inflammation by inactivating NF-κB/p65 through the upregulation of miR-19b-mediated PPARγ in ox-LDL-treated HUVECs." (PMID 41403695, 2025). "Interestingly, myeloid-specific conditional deletion of HDAC3 shifted macrophages to an anti-inflammatory phenotype with improved lipid accumulation and plaque stability in a mouse model of atherosclerosis." (PMID 39050859, 2024). "While HDAC3 is critical for maintaining endothelial layer integrity in the areas of disturbed flow in atherosclerosis, its up-regulation is involved in inflammatory responses in HUVECs and pharmacologic inhibition of HDAC3 mitigates the development of atherosclerotic lesions in mice." (PMID 38397377, 2024). "When HDAC3 is knocked down, ApoE−/− mice develop atherosclerosis, and their vessel ruptures." (PMID 38031118, 2023). "KCNQ1OT1 promoted atherosclerosis development by modulating miR-452-3p/HDAC3/ABCA1 pathway." (PMID 36100884, 2022). "Here, we specifically summarize the impact of HDAC3 and its inhibitors on vascular function, inflammation, lipid accumulation, and plaque stability in the development of atherosclerosis with the hopes of opening up new opportunities for the treatment of cardiovascular diseases." (PMID 35656103, 2022). "In this context, (macrophage-specific) HDAC3 inhibition may be an attractive target for atherosclerosis therapy since its deletion promotes anti-atherogenic macrophage responses while inhibiting inflammatory macrophage cues." (PMID 31736752, 2019). "Similarly, HDAC2 and HDAC3 are key regulators of the following disorders: rheumatoid arthritis, severe asthma and chronic obstructive pulmonary disease, and atherosclerosis." (PMID 30262728, 2018). "In human, atherosclerosis Hdac3 was associated with plaque vulnerability and negatively correlated with pro-fibrotic TGFB1 expression." (PMID 25007801, 2014). "As per the study, the overexpression of HDAC3 attenuated the levels of TNF-α and IL-1β in the arterial tissue in a mouse model of atherosclerosis." (PMID 39050859, 2024). "In contrast, the inhibition of HDAC3 in bone marrow-derived macrophages found in mice raises the levels of ATP-binding cassette transporter A1 (ABCA1), which is involved in atherosclerosis prevention." (PMID 35656103, 2022). "Inhibitors of HDAC3 and HDAC9 significantly reduced atherosclerosis in mouse models." (PMID 40076813, 2025). "However, this lack of HDAC3 in ECs reduces cell survival and accelerates the development of atherosclerosis." (PMID 35656103, 2022). "HDAC3 and HDAC9 are promising targets, and apabetalone, a bromodomain and extraterminal (BET) protein inhibitor, attenuates inflammation, but its efficacy to attenuate atherosclerosis and cardiovascular diseases has not been established yet." (PMID 39796562, 2024).
B-cell lymphomas (26 papers, 2013 to 2025). "Based on a strong rationale that B-cell lymphomas with CREBBP mutations are dependent on HDAC3 activity, HDAC3 inhibition has been recently demonstrated as a promising strategy for those mutant cases while wild-type tumors show modest responses." (PMID 39117798, 2024). "In CREBBP-mutant B-cell lymphoma cells, HDAC3 inhibition shows strong anti-tumor effects via H3K27ac restoration." (PMID 39117798, 2024). "Of note, previous studies revealed that HDAC3 regulates STAT3 in B-cell lymphoma by affecting the STAT3 acetylation level and in turn STAT3 nuclear export." (PMID 37019881, 2023). "In Non-Hodgkin B-cell lymphoma and acute myeloid leukemia, c-Myc was also reported to regulate the gene transcription by recruiting HDAC3, while HDAC1/2 were most likely to be recruited to the promoter of MYC and regulated the transcription of MYC." (PMID 35158730, 2022). "HDAC3 inhibition combined with anti-PD-1/PD-L1 therapy can significantly improve the efficacy of B-cell lymphoma treatment." (PMID 34880761, 2021). "Another study showed that histone deacetylase 3 (HDAC3) inhibitor upregulates PD-L1 expression through epigenetic mechanisms on DCs in the TME in B-cell lymphomas." (PMID 34063096, 2021). "It has also been shown that histone deacetylase 3 (HDAC3) is another important epigenetic regulator of PD-L1 in B-cell lymphoma as its inhibition increases PD-L1 transcription, resulting in a better clinical response to PD-L1 blockade." (PMID 33430146, 2021). "In follicular lymphoma (FL) and diffuse large B cell lymphoma (DLBCL), Bcl6 recruits HDAC3 to repress transcription and trigger B cell lymphoma." (PMID 34926293, 2021). "In aggressive B-Cell lymphomas, Myc, HDAC3, and PRC2 are tethered to the miR-29 promoter regions as a co-repressor complex to down-regulate miR-29 expression through histone deacetylation and trimethylation." (PMID 29221202, 2017). "Myc and HDAC3 are regarded as miR-15a/16 regulators in mantle cells and other non-Hodgkin B-cell lymphomas." (PMID 24887070, 2014). "Moreover, HDAC3 is a crucial regulator of PD-L1 transcription in B-cell lymphomas, and its inhibition increases the response to anti-PD-1 therapy." (PMID 38168914, 2024). "In B-cell lymphoma, HDAC3 is recruited to the PD-L1 promoter by the transcriptional inhibitor BCL6." (PMID 34880761, 2021). "Targeting HDAC3 may be a promising approach for B-cell lymphoma immunotherapy." (PMID 38168914, 2024). "Romidepsin (HDAC1/2 inhibitor), valproic acid (Class I HDAC inhibitor), or RGFP966 (HDAC3 inhibitor) can upregulate MHC class I expression and the expression of costimulatory molecules such as CD80 and CD86 in B-cell lymphomas." (PMID 39620228, 2024). "HDAC3 inhibitor enhances histone acetylation and recruitment of BRD4 at the promoter region of the PD-L1 gene, leading to transcriptional activation in B-cell lymphoma." (PMID 35163049, 2022). "Myc acts as a repressor of miRNA-29 by recruiting histone deacetylase 3 (HDAC3) and EZH2 in aggressive B-Cell lymphomas." (PMID 35892859, 2022). "Selective HDAC3 inhibitors (e.g., RGFP966) also upregulated PD-L1 expression because HDAC3 was shown to repress PD-L1 transcription in B-cell lymphomas." (PMID 32162275, 2020). "Through epigenetic regulation and recruiting histone deacetylase 3 (HDAC3), MYC represses miR-15a/miR-16-1 expression in mantle cell and other non-Hodgkin B-cell lymphomas." (PMID 32549409, 2020). "Valproic acid (class I HDAC inhibitor), romidepsin (HDAC1/2 inhibitor) or RGFP966 (HDAC3 inhibitor) upregulates MHC class I expression and costimulatory molecules, such as CD80 and CD86, in B-cell lymphomas." (PMID 32162275, 2020). "In aggressive B cell lymphoma, miR-29a is repressed by MYC within a co-repressor complex that also includes HDAC3 and EZH2." (PMID 24348513, 2013).
B-cell lymphomas (continued). "Interestingly, a link between the miR-29 family by MYC has been recently reported, as repression of miR-29 by MYC through a corepressor complex with HDAC3 and EZH2 is observed in aggressive B-cell lymphomas." (PMID 26453442, 2015). "In addition to retrotransposon alterations, our integrated analysis of ATAC-seq and RNA-seq further reveals a potential link between GNAS KO plus HDAC3 inhibition and the ETS family transcription factors PU.1 and SpiB for transcriptional regulation of IFN signal activation in B-cell lymphoma." (PMID 39117798, 2024). "Selective HDAC-3 inhibitors have also been shown to up-regulate the expression of PD-L1 in B-cell lymphoma, suggesting that HDAC-3 may be one of the key inhibitors mediating PD-L1 transcription in B-cell lymphoma." (PMID 37304265, 2023). "Interestingly, previous reports suggest a potential cooperativity between BCL6 and chromatin-modifying proteins such as EZH2, LSD1, and the NCOR/HDAC3 complex, suggesting that BCL6 may act as an epigenetic re-programming TF in cancers such as B-cell lymphoma." (PMID 35711675, 2022). "Combined inhibition of HDAC3 and EZH2 induced restoration of miR-29 and suppressed lymphoma cell growth, suggesting the MYC–EZH2–miRNA axis could be a promising target for epigenetic therapy in B cell lymphoma." (PMID 24348513, 2013).
Hepatic steatosis (25 papers, 2013 to 2025). Steatosis is a term used to denote lipid accumulation within hepatocytes. "Specifically, HDAC3 and HDAC8 have been implicated in promoting insulin resistance and β‐catenin activation in MASLD‐associated HCC, while inhibition of HDAC2 and HDAC3 has been shown to ameliorate hepatic steatosis and inflammation in experimental models." (PMID 40693828, 2025). "Liver-specific HDAC3-/- knockout mice show severe hepatic steatosis that is associated with increased de novo lipogenesis and higher insulin sensitivity." (PMID 31139087, 2019). "The nuclear receptor corepressors (N-CoR)/Histone Deacetylase 3 (HDAC3) complex is necessary for repression by Rev-erbα, with liver-specific HDAC3 knockout causing deregulated lipid metabolism and hepatic steatosis in the mouse." (PMID 29662454, 2018). "Histone deacetylase 3 (HDAC3) is an epigenetic regulator associated with hepatic steatosis." (PMID 33167594, 2020). "Depletion of HDAC3 in the liver of adult mice causes remarkable hepatic steatosis, which can be rescued by wild-type (WT) or catalytically inactive mutants of HDAC3, demonstrating that the function of HDAC3 in hepatic lipid metabolism does not require its enzymatic activity." (PMID 30428023, 2019). "For HDAC3, there are important questions about which transcription factors recruit it to the genome, and which HDAC3-associated proteins act as downstream effectors to impact lipid gene regulation and hepatic steatosis." (PMID 28916805, 2017). "Recent studies also have shown that liver-specific knockout of the gene encoding HDAC3 in mice leads to severe hepatic steatosis and increased expression of lipogenic genes, although whether HDAC3 expression or function is altered by ethanol has yet to be elucidated." (PMID 24313164, 2013). "Adults display mild hepatic steatosis, suggesting a requirement for HDAC3 enzymatic function in the adult liver; however, the phenotype is much less severe than for Hdac3 conditional deletion in the liver." (PMID 41416925, 2025). "The co-localization of the circadian nuclear receptor REV-ERBα with HDAC3 has been shown to regulate lipid metabolism which is further evidenced by the occurrence of hepatic steatosis in mice with selective deletion of either HDAC3 or REV-ERBα in the liver." (PMID 39335475, 2024). "Taken together, HDAC3 and NCoR1 KO in the liver contributes to metabolic imbalances, resulting in hepatic steatosis, insulin resistance, altered glucose and lipid metabolism." (PMID 37674539, 2023). "It is key to highlight that HDAC3 also has direct interaction with molecules that participate in the development of hepatic steatosis, such as SREBP1, key molecule in the lipogenic process." (PMID 35087844, 2021). "HDAC3 downregulates the expression of genes related to fatty acid uptake, TG synthesis, and lipolysis, thus preventing hepatic steatosis." (PMID 34681759, 2021). "Recruitment through the NCoR–HDAC3 complex with REV-ERBα and hepatocyte nuclear factor 6 (HNF6) to lipogenic genes enhancers impacts on lipid metabolism so that Hdac3 and REV- ERBα-deficient mice display hepatic steatosis." (PMID 31718031, 2019). "Recent studies demonstrated that HDAC3 negatively regulates hepatic steatosis by regulating lipid metabolism genes via several mechanisms." (PMID 30214048, 2018). "Recently, other mechanisms involved in HDAC3-mediated inhibition of hepatic steatosis have been elucidated." (PMID 30214048, 2018).
Hepatic steatosis (continued). "Mice with a liver-specific deletion of Hdac3 display an increased expression of de novo lipogenesis enzymes due to a constitutively active transcriptional environment, resulting in fatty liver disease and elevated serum cholesterol." (PMID 29445033, 2018). "HDAC3 is an important regulator of hepatic lipid metabolism in a circadian manner and invalidation of its gene induces hepatic steatosis." (PMID 26925174, 2016). "Indeed, liver KO of NCoR and RevErb mice showed liver steatosis phenotype, resembling that of the liver HDAC3-KO mice." (PMID 37674539, 2023). "HDAC3 is recruited to the promoter of PPARγ2 by retinoic acid receptor-related orphan receptor-α and represses PPARγ2 expression by deacetylation, thereby downregulating the expression of its target fatty acid uptake genes and preventing hepatic steatosis." (PMID 33167594, 2020). "Indeed, knockouts and various knockin mutants of NCoR, SMRT, and HDAC3 have demonstrated hepatic steatosis phenotypes, in contrast to the lipid overload-protected phenotype observed here with hepatocyte Bcl6 ablation." (PMID 30983568, 2019). "The physiological role of HDAC3 has been reported to repress hepatic steatosis." (PMID 28757615, 2017). "Interestingly, conditional deletion of HDAC3 in osteoprogenitor cells has been shown to attenuate high-fat diet-induced insulin resistance, hepatic steatosis, and metabolic syndrome." (PMID 27904654, 2016). "This is controlled by histone deacetylase 3 (HDAC3), and its depletion promotes the development of hepatic steatosis." (PMID 40867875, 2025). "More interestingly, the DADm mice showed no signs of hepatic steatosis in contrast to the HDAC3-KO mice, and the authors claimed that the phenotype is independent of HDAC3 deacetylase activity." (PMID 37674539, 2023). "Depleting HDAC3 or PROX1 in the liver increases hepatic TGs and results in hepatic steatosis." (PMID 30214048, 2018). "The beneficial effect of MS-275 in fatty liver might be mediated by inhibition of HDAC1/2 rather than HDAC3." (PMID 36077368, 2022).
leukemia (25 papers, 2009 to 2025). A malignant (clonal) hematologic disorder, involving hematopoietic stem cells and characterized by the presence of primitive or atypical myeloid or lymphoid cells in the bone marrow and the blood. "The functional role of HDAC3 in leukemia has been attributed to its association with the PML–RAR fusion protein in a deacetylase-dependent fashion." (PMID 19204783, 2009). "To evaluate a possible anti-leukemic effect of HDAC3 inhibition in vivo we utilized the SKNO1 leukemia model bearing a RUNX1-RUNX1T1 translocation and ELF-153 complex karyotype AML, which are both addicted to ERG expression and dependent on HDAC3 activity." (PMID 37735473, 2023). "Strikingly, leukemia development was abrogated in mice transplanted with SKNO1 cells with reduced expression of HDAC3 (follow-up of 45 days)." (PMID 37735473, 2023). "Highlighting this interaction as a potential therapeutic target, HDAC3 inhibition led to reduced growth of ERG-dependent leukemia cells in vitro and in vivo." (PMID 37735473, 2023). "Inhibition of HDAC3 is conducive to reversing the chemoresistance of leukemia cells and the MEKi resistance of PDAC cells." (PMID 37743465, 2023). "More recently, bakkenolide A was discovered to be active against leukemia, by inhibiting the synthesis of histone deacetylase (HDAC3)." (PMID 36987011, 2023). "HDAC3 expression of primary leukemia cells from 17 AML patients (de novo samples and relapsed samples) were detected by q-PCR." (PMID 33298132, 2020). "MS‐275, which preferentially targets HDAC1 and HDAC3, is reported to induce acute ROS in human leukemia cells." (PMID 31668005, 2019). "Authors of a recent study in leukemia cells concluded that HDAC3 activates AKT by deacetylating AKT at K20." (PMID 29523594, 2018). "Sp1 forms a complex with NF-κB to downregulate miR-29b expression through the recruitment of histone deacetylase (HDAC) 1 and HDAC3 in leukemia and thereby contributes to the growth of leukemia cells." (PMID 24519909, 2014). "Currently, there is an increasing interest in HDAC3 as a promising therapeutic target in multiple myeloma, leukemia, and gastric cancer." (PMID 25521755, 2014). "Moreover, HDAC3 enhances the DNA damage repair capability of leukemia cells through activating AKT and thereby protecting leukemia cells from chemotoxicity, suggesting that HDACs can participate in drug resistance by facilitating DNA damage repair." (PMID 35656547, 2022). "To investigate whether chidamide-induced anthracycline-resistant AML cells inhibition was associated with the inactivation of HDAC3 in an AKT-dependent manner, we overexpressed HDAC3 or AKT after chidamide-induced leukemia inhibition." (PMID 33298132, 2020). "Additionally, it has been shown that HDAC3 knockdown dramatically reduces leukemia and lymphoma cell proliferation." (PMID 29523594, 2018). "Furthermore, it was stated that several chemotherapeutic drugs can enhance HDAC class I expression; for example, doxorubicin and cytarabine induce HDAC3 expression in leukemia cells (K562 and THP-1), contributing to acquired resistance as HDAC3 is critical for DNA damage control." (PMID 34944663, 2021). "Previous studies have identified that histone deacetylase 3 (HDAC3) enhances the DNA damage repair by activating AKT and preventing leukemia cells from chemotoxicity." (PMID 41479777, 2025). "Chidamide is an oral selective histone deacetylase (HDAC) inhibitor that selectively inhibits HDAC1, HDAC2, HDAC3, and HDAC10, inducing apoptosis and growth arrest in leukemia cells." (PMID 39040100, 2024). "Interestingly, leukemia-associated pathways that were regulated by ERG in murine fetal liver-derived HSPCs (Hoxa9-Meis1, CBFA2T3, and repression of myeloid differentiation genes) were ranked at the leading edge of gene sets that were significantly perturbed after HDAC3 inhibition." (PMID 37735473, 2023).
leukemia (continued). "The same experiment performed using the leukemia cell line MV4-11 validated HDAC1 (Kdapp = 16 μM), HDAC2 (Kdapp = 14 μM), and HDAC6 (Kdapp = 21 μM) and identified HDAC3 (Kdapp = 13 μM) and HDAC10 (Kdapp = 5 μM) as additional targets of (R/S)-LM." (PMID 37322067, 2023). "In leukaemia cells, chemotherapeutic drugs up‐regulate HDAC3 expression, and HDAC3 deacetylates AKT at K20, thereby promoting AKT phosphorylation, accelerating leukaemia progression and inducing chemotherapeutic resistance in MLL‐AF9(+) leukaemia cells." (PMID 39778006, 2025). "In contrast, HDAC3 inhibition in THP1 cells had no negative effect on leukemia development in vivo." (PMID 37735473, 2023). "To investigate the significance of Class I HDACs (HDAC1, HDAC2, HDAC3, and HDAC8), HDAC11, and Klfs (Klf1, KLf3, Klf4, and Klf7) in the pathogenesis of human leukemia, we used real-time RT-PCR to evaluate the expression of HDACs and Klfs in bone marrow samples from human leukemia patients." (PMID 25341045, 2014). "Our findings regarding elevated expression of Hdac3 and Rbbp4 in fetal but not adult pre-leukemic cells compared to WT may also have implications for the design of treatment schemes involving HDAC inhibitors for infant and adult leukemia." (PMID 38555405, 2024).